CHRDL1 (chordin like 1)
Description:
Antagonizes the function of BMP4 by binding to it and preventing its interaction with receptors. Alters the fate commitment of neural stem cells from gliogenesis to neurogenesis. Contributes to neuronal differentiation of neural stem cells in the brain by preventing the adoption of a glial fate. May play a crucial role in dorsoventral axis formation. May play a role in embryonic bone formation (By similarity). May also play an important role in regulating retinal angiogenesis through modulation of BMP4 actions in endothelial cells. Plays a role during anterior segment eye development.
Synonyms: NRLN1; CHL; MGC1; MGCN; VOPT; dA141H5.1
Tractability: Antibody: UniProt places it where antibodies can reach, with high confidence; its Gene Ontology location is reachable by antibodies, with high confidence; UniProt predicts a signal peptide or a membrane-spanning region.
Gene: Protein-coding gene on chromosome X (110,673,856 to 110,796,192, reverse strand). Ensembl gene ENSG00000101938.
Subcellular location: Secreted
Pathways (Reactome):
Metabolism of proteins: Post-translational protein phosphorylation; Regulation of Insulin-like Growth Factor (IGF) transport and uptake by Insulin-like Growth Factor Binding Proteins (IGFBPs)
Signal Transduction: Signaling by BMP
Gene Ontology:
Molecular function: BMP binding
Biological process: eye development; cell differentiation; negative regulation of BMP signaling pathway; developmental process
Cellular component: endoplasmic reticulum lumen; extracellular region
Homologues: Orthologues: chimpanzee CHRDL1 (100% identical), macaque CHRDL1 (99% identical), dog CHRDL1 (97% identical), guinea pig CHRDL1 (97% identical), pig CHRDL1 (96% identical), rabbit CHRDL1 (90% identical), mouse Chrdl1 (88% identical), rat Chrdl1 (88% identical), tropical clawed frog chrdl1 (56% identical). Paralogues in human: CHRDL2 (36% identical), MUC5B (22% identical), MUC5AC (21% identical), OTOGL (21% identical), OTOG (21% identical), VWF (20% identical), FCGBP (20% identical), ZAN (19% identical), MUC2 (18% identical), MUC6 (18% identical), MUC19 (18% identical), TECTA (17% identical), and 7 more.
Diseases named in the same sentence as CHRDL1 in open-access papers:
CHRDL1 is named in the same sentence as 74 diseases in open-access papers, as found by Europe PMC text mining. Sharing a sentence is not in itself a finding about the gene and the disease. The quoted sentences say what the papers report.
breast carcinoma (18 papers, 2015 to 2025). "Recent studies have associated CHRDL1 with various cancers, including breast cancer, lung cancer, gastric cancer, thyroid cancer, T-cell acute lymphoblastic leukemia (T-ALL), melanoma, and OSCC." (PMID 35494000, 2022). "Similarly, elevated CHRDL1 expression has been associated with significantly better long-term survival rates in both breast cancer and gastric cancer." (PMID 40837015, 2025). "High CHRDL1 expression is associated with better clinical outcomes in patients with breast cancer." (PMID 35494000, 2022). "Previous studies have identified CHRDL1 as a negative regulator that primarily suppresses breast cancer cell migration and invasion." (PMID 40837015, 2025). "The expression of CHRDL1 is downregulated in gastric cancer, thyroid cancer, lung cancer, malignant melanoma, and breast cancer." (PMID 40837015, 2025). "CHRDL1 has been demonstrated to exert its effects in various breast cancer cell lines by antagonizing the BMP/SMAD signaling pathway." (PMID 40837015, 2025). "Consistently, CHRDL1 was found to be a prognostic biomarker of better outcomes in patients with breast cancer." (PMID 35205284, 2022). "For example, it is known that BMP4 can exert pro-tumourigenic functions in breast cancer, where it mediates migration and invasion, which can be blocked via CHRDL1, whereas CHRDL1 induces the neuronal differentiation of neural stem cells." (PMID 36497175, 2022). "Chordin-like 1 is a negative regulator of bone morphogenetic protein 4-induced migration and invasion in breast cancer." (PMID 33585078, 2021). "Although CHRDL1 has been reported to act as a tumor suppressor in breast cancer, there are few studies ofCHRDL1 in gastric cancer." (PMID 28423564, 2017). "Here we show that the EMT-inducer ZEB1 activates the expression of genes, previously associated with breast cancer bone metastasis, including the BMP-inhibitors NOG, FST and CHRDL1." (PMID 25973542, 2015). "Additionally, CHRDL1 shows prognostic value in breast cancer, thyroid cancer, and clear cell renal carcinoma." (PMID 40230414, 2025). "In breast cancer, CHRDL1 inhibits BMP4-induced cell migration." (PMID 40230414, 2025). "In addition, CHRDL1 seems to function as an inhibitor of tumor growth and metastasis in breast cancer, and breast cancer patients with high CHRDL1 expression have better prognosis." (PMID 38188687, 2023). "Activation of EMT was also found in gastric cancer and breast cancer cells after CHRDL1 silencing." (PMID 35494000, 2022). "CHRDL1 was proven to block BMP-induced increases in breast cancer cell migration and invasion." (PMID 35494000, 2022). "Recently, researchers found that CHRDL1 could participate in the progression of several tumors, such as malignant melanoma, leukemia, breast cancer and gastric cancer." (PMID 35021154, 2022). "In breast cancer and thyroid cancer, patients with high CHRDL1 had a poorer prognosis." (PMID 35021154, 2022). "In breast cancer, CHRDL1 could suppress cell migration and invasion by inhibiting BMP signaling." (PMID 36776317, 2023). "CHRDL1 was reported to be downregulated in T-ALL, gastric cancer, thyroid cancer, lung cancer, malignant melanoma, and breast cancer." (PMID 35494000, 2022). "It has been demonstrated that both endogenous CHRDL1 and recombinant CHRDL1 suppress the migration and invasion induced by BMP4 signaling in different breast cancer cell lines." (PMID 35494000, 2022). "Chordin-like 1(CHRDL1), as a secreted antagonist of BMP signaling, has been previously reported to predominantly suppress BMP4-induced migration and invasion, and its higher expression indicates better clinical outcomes in breast cancer." (PMID 34745928, 2021). "Chrdl1 can hinder the BMP-mediated enhanced invasion and migration of breast cancer cells." (PMID 33447177, 2020).
breast carcinoma (continued). "In the bone tropic cells, NOG, FST and CHRDL1 are all positively regulated by ZEB1, whereas in different parental breast cancer cell lines only NOG and CHRDL1 are effectively targeted by ZEB1 and an antagonistic regulatory mechanism between NOG and FST seems to dominate and determine FST expression." (PMID 25973542, 2015). "Our study demonstrated that CHRDL1 overexpression suppresses the migration and adhesion of pancreatic cancer cells (PANC-1 and SW1990) without significantly affecting their proliferation, which aligns with the reported effects of CHRDL1 in breast cancer and melanoma cells." (PMID 40837015, 2025). "Moreover, CHRDL1 could inhibit cell migration and invasion by suppressing BMP signaling in breast cancer." (PMID 33980221, 2021).
gastric cancer (11 papers, 2017 to 2025). A primary or metastatic malignant neoplasm involving the stomach. "Herein, we report that CHRDL1 expression was significantly down-regulated in gastric cancer tissues and associated with poor survival." (PMID 28423564, 2017). "Furthermore, CHRDL1 expression is significantly downregulated in gastric cancer tissues and associated with poor survival, and CHRDL1 knockdown promotes tumor cell proliferation and migration through BMPR II by activating Akt, Erk, and β-catenin." (PMID 35494000, 2022). "Additionally, low expression of CHRDL1 was associated with worse survival among 100 patients with gastric cancer." (PMID 33980221, 2021). "Next, we investigated the underlying cause of low CHRDL1 expression in gastric cancer." (PMID 28423564, 2017). "Studies have shown that CHRDL1 promotes the proliferation and migration of gastric cancer cells by antagonizing BMPR II." (PMID 40837015, 2025). "Promoter hypermethylation was found to repress CHRDL1 gene in gastric cancer and its downregulation facilitates the proliferation and metastasis of cancer cells." (PMID 38188687, 2023). "CHRDL1 knockdown promotes the proliferation and migration of gastric cancer cells through BMPR II by activating Akt, Erk, and β-catenin." (PMID 35494000, 2022). "In our work, we determined that CHRDL1, a secreted protein, was markedly down-regulated in gastric cancer samples." (PMID 28423564, 2017). "The migration of gastric cancer cells was markedly inhibited by CHRDL1 over expression both in vitro and in vivo." (PMID 28423564, 2017). "We also detected CHRDL1 expression in gastric cell lines and found that it was down-regulated in most gastric cancer cell lines, especially in NCI-N87 and MNK-45 compared with GSE-1." (PMID 28423564, 2017). "To investigate the mechanism by which CHRDL1was down-regulated in gastric cancer, we measured the promoter methylation status of CHRDL1 and observed hypermethylation in most gastric cancer samples relative to adjacent non-tumor tissues." (PMID 28423564, 2017). "From these data, we concluded that the hypermethylation status of the CHRDL1 promoter in gastric cancer decreased CHRDL1 secretion in the supernatant, which promoted BMP binding to BMPR II and the subsequent activation of Akt and Erk." (PMID 28423564, 2017). "To explore CHRDL1 expression in gastric cancer progression, we performed qPCR on 61 pairs of gastric cancer tissues and non-tumor tissues." (PMID 28423564, 2017). "We further analyzed the correlation between clinic-pathological parameters and CHRDL1 expression in gastric cancer patients." (PMID 28423564, 2017). "First, methylation-specific PCR (MSP) was used to determine the methylation status of the CHRDL1 promoter in gastric cancer patients." (PMID 28423564, 2017). "In our research, we observed that CHRDL1 expression was significantly down-regulated in gastric cancer and regulated by methylation status." (PMID 28423564, 2017). "However, this contrasts with findings in gastric cancer, where CHRDL1 was shown to inhibit proliferation, suggesting tissue-specific differences in CHRDL1-mediated signaling." (PMID 40837015, 2025). "In addition, these authors reported that the knockdown of CHRDL1 induced cell proliferation and metastasis via the activation of Akt and Erk, suggesting that CHRDL1 plays a tumor suppressor role in gastric cancer." (PMID 33980221, 2021). "Next, we determined which pathway mediated the effects of CHRDL1 on gastric cancer." (PMID 28423564, 2017). "Furthermore, we observed the hypermethylation of the CHRDL1 promoter in gastric cancer, which induced low expression of CHRDL1 and decreased its secretion to the supernatant." (PMID 28423564, 2017). "Therefore, the relationship between serum CHRDL1 levels and the prognosis of gastric cancer patients requires further investigation." (PMID 28423564, 2017). "IHC also confirmed the down-regulation of CHRDL1 in gastric cancer tissues." (PMID 28423564, 2017).
gastric cancer (continued). "Besides, down-regulation of CHRDL1 was observed in breast and gastric cancer." (PMID 35021154, 2022). "Therefore, CHRDL1 methylation status may represent a novel biomarker to identify and predict the prognosis of gastric cancer patients CHRDL1." (PMID 28423564, 2017). "Finally, we explored whether CHRDL1 could affect gastric cancer tumorigenesis and tumor cell metastasis in vivo." (PMID 28423564, 2017). "Thus, low CHRDL1 expression promotes cell metastasis through BMP4 in gastric cancer." (PMID 28423564, 2017). "CHRDL1, a BMP4 antagonist, has tumor-suppressive effects in breast and gastric cancers, but its role in pancreatic cancer is unclear." (PMID 40837015, 2025). "Lastly, colorectal and gastric cancers exhibit a shared emphasis on the genes DES, RNF150, and CHRDL1, highlighting a common gene influence pattern." (PMID 39596491, 2024). "The Kaplan-Meier plot of TCGA data base and our clinical samples both demonstrated that patients with low CHRDL1 expression exhibited poorer survival than those with high CHRDL1 expression, suggesting that CHRDL1 expression might act as a prognostic factor in patients with gastric cancer." (PMID 28423564, 2017). "Collectively, these data demonstrate that low CHRDL1 expression activates Akt, Erk and induces cell proliferation and migration through BMP4 in gastric cancer." (PMID 28423564, 2017). "The hypermethylation status of the CHRDL1 promoter observed in our study explained the low expression of CHRDL1 in gastric cancer tissues as compared with adjacent non-tumor tissues." (PMID 28423564, 2017). "However, our study is limited by the fact that we did not measure CHRDL1 levels in the serum of gastric cancer patients." (PMID 28423564, 2017).
melanoma (7 papers, 2020 to 2025). A malignant, usually aggressive tumor composed of atypical, neoplastic melanocytes. "We were excited to find for the first time that FCGR2, CHRDL1, SLC5A3 are associated with the prognosis of melanoma." (PMID 40652057, 2025). "Specifically, low CHRDL1 expression is correlated with poor survival outcomes in melanoma and LUAD, while the opposite is true in BLCA and COAD." (PMID 40230414, 2025). "Early investigations also suggested that CHRDL1 play a tumor-suppressive role in melanoma and triple-negative breast cancers." (PMID 38188687, 2023). "In melanoma, CHRDL1 showed growth-suppressing properties in melanoma-derived cell lines with DNA methylation and genomic deletion." (PMID 35494000, 2022). "In malignant melanoma, CHRDL1 was identified aa a tumour-suppressor gene and was significantly down-regulated in melanoma cell lines." (PMID 35021154, 2022). "CHRDL1 mRNA has been reported to have tumor suppressing effects on melanoma and TNBC." (PMID 33542899, 2020).
lung adenocarcinoma (6 papers, 2021 to 2025). A carcinoma that arises from the lung and is characterized by the presence of malignant glandular epithelial cells. "Based on BMP5 and closely related hub genes such as CHRDL1, GIMAP8, and KAL1, we constructed and improved a prognostic risk model that effectively evaluated the prognosis of lung adenocarcinoma." (PMID 34745928, 2021). "First, CHRDL1 as a BMP signaling antagonist suppresses tumor metastasis but co-expressed with BMP5 in lung adenocarcinoma." (PMID 34745928, 2021). "Additionally, the study aimed to further validate the mechanistic role of CHRDL1 in lung adenocarcinoma (LUAD), clarifying its contribution to tumorigenesis and evaluating its potential as a therapeutic target for LUAD." (PMID 40230414, 2025). "Chordin-like 1 (CHRDL1), an inhibitor of bone morphogenetic proteins(BMPs), has been recently reported to participate in the progression of numerous tumors, however, its role in lung adenocarcinoma (LUAD) remains unclear." (PMID 35021154, 2022). "These gaps in knowledge are especially evident in lung adenocarcinoma (LUAD), a major subtype of non-small cell lung cancer (NSCLC), where CHRDL1’s function has yet to be fully elucidated." (PMID 40230414, 2025). "It is necessary for CHRDL1 to explore the regulatory relationship of CHRDL1 with BMP5 and its role in lung adenocarcinoma." (PMID 34745928, 2021). "Interestingly, CHRDL1, the BMP antagonist, was found to be co-expressed with BMP5, and both were screened for their significant prognostic protective value in lung adenocarcinoma in the current study." (PMID 34745928, 2021).
thyroid cancer (6 papers, 2020 to 2025). "CHRDL1 was found to be less expressed in thyroid cancer using the IHC method, and CHRDL1 was closely correlated with disease-free survival (DFS) of patients with thyroid cancer." (PMID 33980221, 2021). "The Human Protein Atlas (HPA)-based Immunohistochemistry (IHC) database showed that FN1, NMU, and ITGA2 were upregulated in thyroid cancer tissues compared with normal tissues, while CHRDL1, GNAI1 and GNA14 were downregulated in thyroid cancer tissues." (PMID 32337286, 2020). "Among the top 30 hub genes obtained in PPI network, the expression levels of FN1, NMU, CHRDL1, GNAI1, ITGA2, GNA14 and AVPR1A were associated with the prognosis of thyroid cancer." (PMID 32337286, 2020). "The abnormal expression of chordin-like 1 (CHRDL1) is identified in many cancers, while the effect of CHRDL1 in thyroid cancer (THCA) remains unclear." (PMID 36749222, 2023). "Since no research has proved that CHRDL1 is related to thyroid cancer, more research is needed to verify the association between CHRDL1 and thyroid cancer and evaluate CHRDL1 as a target for thyroid cancer treatment." (PMID 32337286, 2020). "Using data mining based on bioinformatics tools, the present study has confirmed CHRDL1, GNAI1, GNA14 and AVPR1A are associated with thyroid cancer although their specific biological functions have not been explored by the molecular biology methods." (PMID 32337286, 2020). "Hence, we derived seven key genes related to the prognosis of thyroid cancer: FN1, NMU, CHRDL1, GNAI1, ITGA2, GNA14, AVPR1A." (PMID 32337286, 2020).